PXK (PX domain containing serine/threonine kinase like)
Description:
Binds to and modulates brain Na,K-ATPase subunits ATP1B1 and ATP1B3 and may thereby participate in the regulation of electrical excitability and synaptic transmission. May not display kinase activity.
Synonyms: MONaKA; FLJ20335; Slob
Tractability: Antibody: UniProt places it where antibodies can reach, with high confidence; its Gene Ontology location is reachable by antibodies, with high confidence; the Human Protein Atlas places it where antibodies can reach. PROTAC: ubiquitination databases record sites on it; its protein half-life has been measured.
Gene: Protein-coding gene on chromosome 3 (58,332,686 to 58,426,746, forward strand). Ensembl gene ENSG00000168297.
Subcellular location: Cytoplasm; Cell membrane
Subcellular location (Human Protein Atlas): Cytosol; Centriolar satellite; Plasma membrane
Gene Ontology:
Molecular function: ATP binding; nucleotide binding; protein kinase activity; actin binding; phosphatidylinositol binding
Biological process: inflammatory response; modulation of chemical synaptic transmission
Cellular component: cytoplasm; cytosol; plasma membrane; protein-containing complex
Genetic constraint (gnomAD): Loss-of-function variants: 24 observed, 57.38 expected, observed/expected ratio (o/e) 0.42, 90% interval 0.3 to 0.59. The upper end of that interval is the gene's LOEUF score, 0.59, which puts it in group 2 of 6, group 1 being the genes least tolerant of losing a copy. Missense variants: 537 observed, 588.69 expected, observed/expected ratio (o/e) 0.91, 90% interval 0.85 to 0.98. Synonymous variants: 221 observed, 221.36 expected, observed/expected ratio (o/e) 1, 90% interval 0.89 to 1.12.
Homologues: Orthologues: chimpanzee PXK (100% identical), macaque PXK (99% identical), dog PXK (97% identical), pig PXK (97% identical), rabbit PXK (96% identical), rat Pxk (93% identical), mouse Pxk (93% identical), guinea pig PXK (88% identical), tropical clawed frog pxk (82% identical), zebrafish pxk (72% identical), Drosophila melanogaster CG8726 (42% identical). Paralogues in human: SNX16 (12% identical).
Diseases named in the same sentence as PXK in open-access papers:
PXK is named in the same sentence as 16 diseases in open-access papers, as found by Europe PMC text mining. Sharing a sentence is not in itself a finding about the gene and the disease. The quoted sentences say what the papers report.
rheumatoid arthritis (6 papers, 2014 to 2024). A chronic, systemic autoimmune disorder characterized by inflammation in the synovial membranes and articular surfaces. "This SNP and the PXK gene are associated with rheumatoid arthritis and the systemic lupus erythematosus (SLE), that are related to the male fertility." (PMID 33921254, 2021). "Genome wide association studies have identified variants in PXK that confer risk for humoral autoimmune diseases, including systemic lupus erythematosus (SLE or lupus), rheumatoid arthritis and more recently systemic sclerosis." (PMID 25620976, 2014). "The other four candidate targets with a link to autoimmunity are DAPK1 (inflammatory bowel disease), MST4 (Grave’s disease), PXK (systemic lupus erythematosus), and IRAK3 (rheumatoid arthritis) (for literature evidence check S1 Table)." (PMID 32459810, 2020).
systemic lupus erythematosus (5 papers, 2012 to 2021). An autoimmune multi-organ disease typically associated with vasculopathy and autoantibody production. "While ABHD6 eQTLs were shown to correlate with lupus-association, there were also PXK eQTLs that were associated with lupus." (PMID 25620976, 2014). "Taken together, these data define a new candidate mechanism for the genetic association of variants around PXK with lupus risk and highlight the regulation of intracellular trafficking as a genetically regulated pathway mediating human autoimmunity." (PMID 25620976, 2014). "Taken together, our work supports a model in which PXK increases lupus risk through the regulation of BCR internalization." (PMID 25620976, 2014). "Overall, we identified a limited haplotype of highly associated variants in the promoter and first exon of PXK that account for all of the lupus-association in the region." (PMID 25620976, 2014). "In this study, we identify a 257 kb region on chromosome 3, including all of PXK and a large region upstream of the gene that contains the lupus association signal." (PMID 25620976, 2014). "The PXK locus remains complicated and future work will be important to continue to unravel the specific genetic variations underlying the lupus association." (PMID 25620976, 2014). "Using a genome-wide association study (GWAS) design, we first identified association of a single nucleotide polymorphism (SNP) in the PXK locus with the occurrence of lupus in women of European descent." (PMID 25620976, 2014). "We then tested the hypothesis that the lupus-associated risk variants at the PXK locus affected the rate of BCR internalization by measuring the internalization of the BCR in cells derived from individuals with known genotypes." (PMID 25620976, 2014). "It remained possible that rare variants were driving the lupus association at the PXK locus." (PMID 25620976, 2014). "The PXK locus association with lupus-risk has since been replicated in several studies." (PMID 25620976, 2014). "We genotyped 57 useful markers from the PXK locus in a transancestral group of 18,286 lupus cases and controls." (PMID 25620976, 2014). "Furthermore, we identified an allelic decrease in PXK-BCR co-localization and BCR internalization in subjects expressing the lupus-risk haplotype." (PMID 25620976, 2014). "Based on its role in regulating EGFR, we hypothesized that PXK participates in BCR internalization and lupus-associated variants in the PXK locus differentially regulate BCR internalization." (PMID 25620976, 2014). "Given the expression of PXK in B cells, the fact that PXK has been shown to play a role regulating cell surface receptor expression, and the importance of B cells to the pathology of lupus, we hypothesized that PXK participates in the internalization of the BCR." (PMID 25620976, 2014). "While PXK is involved in trafficking of epidermal growth factor Receptor (EGFR) in COS-7 cells, mechanisms linking PXK to lupus pathophysiology have remained undefined." (PMID 25620976, 2014). "To assess the role of PXK in the BCR internalization phenotype, we decreased PXK expression using shRNA by transfecting 5 study-derived cell lines from patient without lupus with shRNA targeted against PXK or scrambled controls." (PMID 25620976, 2014). "Most of the retrieved genes were of strong interest however some, such as the gene PXK, were not directly related to anti-viral response but to lupus, an autoimmune condition which induces also inflammation." (PMID 22373375, 2012).
autoimmunity diseases (1 paper, 2022). "As for the protective prognostic factors in our study, PXK encoding protein is involved in ligand-induced internalization, synaptic transmits, and degradation of epidermal growth factor receptors associated with some autoimmunity diseases." (PMID 35774514, 2022).
cancer (2 papers, 2012 to 2014). A tumor composed of atypical neoplastic, often pleomorphic cells that invade other tissues. "CDK5R2, NEK9, PRKCA, PXK and STK11 have significant effects on growth of cancer cells in all cancer cell lines." (PMID 22761558, 2012).
PXK also shares sentences with these, for which no sentence is quoted: Autoimmunity (2 papers); systemic sclerosis (2); thyroid cancer (2); celiac disease (1); clear cell carcinomas (1); Graves disease (1); idiopathic inflammatory myopathies (1); inflammatory bowel disease (1); osteoporosis (1); pancreatic cancer (1); Spinocerebellar Ataxia 15 (1); tumor (1).